INHBB (inhibin subunit beta B)
Diseases named in the same sentence as INHBB in open-access papers (continued):
Sharing a sentence is not in itself a finding about the gene and the disease.
colorectal tumors (2 papers, 2009 to 2022). "Clinically, miR-34 targets showed upregulation in primary colorectal tumors (1–2 fold as compared to healthy colorectal tissue) and their expression was correlated with lymph-node metastases (INHBB, AXL, FGFR1, and PDFGRB) and survival (INHBB and AXL)." (PMID 36429127, 2022).
epithelial ovarian cancer (2 papers, 2021 to 2024). "The TGF‐β superfamily member activin, a dimer of the gene products of INHBA and/or INHBB, has been implicated in immune cell maturation and recruitment, but its immune impact within epithelial ovarian cancer (EOC) is not well characterized." (PMID 39248018, 2024).
esophageal cancer (2 papers, 2020 to 2023). A primary or metastatic malignant neoplasm involving the esophagus. "We found that INHBB was up-regulated in digestive system cancers including gastric, colorectal, and esophageal cancers." (PMID 37858201, 2023).
glioblastoma (2 papers, 2025). The most malignant astrocytic tumor (WHO grade IV). "INHBB, a member of the TGF-β family, influences DNA synthesis in various tumors and promotes proliferation and invasiveness in glioblastoma." (PMID 41153362, 2025).
melanoma (2 papers, 2012 to 2022). A malignant, usually aggressive tumor composed of atypical, neoplastic melanocytes. "By qPCR, we validated the upregulation of two genes, INHBB and PLAU, in three additional melanoma cell lines." (PMID 23077590, 2012).
preeclampsia (2 papers, 2022 to 2025). Preeclampsia is a hypertensive disorder of pregnancy that is characterized by new-onset hypertension with proteinuria presenting after 20 weeks of gestation, and depending on mild or severe forms may initially present with severe headache, visual disturbances, and hyperreflexia. "Genetic variants of INHBB have also been associated with preeclampsia, which has also been linked to altered serum urate levels." (PMID 36235682, 2022). "Indeed, our own MR findings suggest no causal relationship between circulating INHBB and preeclampsia (p = 0.1470)." (PMID 40991151, 2025).
prostate tumors (2 papers, 2022 to 2024). "However, the mechanism of action for INHBB in preventing prostate tumors is unknown." (PMID 37981656, 2024). "The findings from Oncomine and FireBrowse analysis of RNA expression are consistent with our protein expression results showing INHBB expression is higher, and INHBC is lower, in prostate tumours when compared to healthy prostate." (PMID 36612143, 2022).
adenoma (1 paper, 2009). A neoplasm arising from the epithelium. "Hypermethylation of at least one of the CpG islands analysed (EN1, SCTR, INHBB) occurred in most carcinomas (90%), with EN1 methylated in 73 and 40% of carcinomas and adenomas, respectively." (PMID 19384295, 2009).
carcinoid tumor (1 paper, 2022). A slow growing neuroendocrine tumor, composed of uniform, round, or polygonal cells having monotonous, centrally located nuclei and small nucleoli, infrequent mitoses, and no necrosis. "(E) Schematic of sensor and signal genes expressed by a ‘composite’ carcinoid tumor cell (T) from data in D. Genes shown are those expressed in>15% of the profiled tumor cells, plus POMC (14% of tumor cells), INHBB (14%), and OPNSW1 (6%)." (PMID 36469459, 2022).
cholesteatoma (1 paper, 2023). A pathologic process characterized by the proliferation of keratinizing squamous epithelium resulting in the accumulation of keratin and cells in the middle ear and/or mastoid. "To elucidate the expression of INHBA, INHBB, and INHA in cholesteatoma mouse model fibroblasts, we collected fibroblasts from the cholesteatoma mouse model and control mouse ear pinnae via cell sorting." (PMID 37537159, 2023). "The results showed that INHBA was significantly upregulated relative to INHBB and INHA in cholesteatoma fibroblasts." (PMID 37537159, 2023). "Therefore, we compared the expression patterns of INHBA, INHBB, and INHA in human cholesteatoma fibroblasts by ddPCR." (PMID 37537159, 2023).
diabetes (1 paper, 2025). "INHBB promotes tumor progression, and therapeutic inhibition of its receptor with bimagrumab demonstrated effective antitumor responses in diabetic mouse models, suggesting INHBB as a novel therapeutic target for pancreatic cancer comanaged with diabetes." (PMID 41516233, 2025). "The poor prognosis of pancreatic cancer patients with comorbid diabetes is mechanistically linked to the expansion of senescent endothelial cells within the TME and their secretion of the TGF-β (transforming growth factor-β) family SASP factor INHBB (inhibin-β B subunit)." (PMID 41516233, 2025).
diabetic nephropathy (1 paper, 2023). "Higher INHBB was found in a polycystic kidney disease mouse model compared to controls, and higher INHBC expression was found in a diabetic nephropathy rat model." (PMID 37365616, 2023).
endometrial adenocarcinoma (1 paper, 2022). "Cysteine mutations in TGFB2, INHA, and INHBB associated with endometrial adenocarcinoma plus cysteine mutations in TGFB2 and TGFB3 with Loeys–Dietz syndrome lead to the hypothesis that TGFB2 is capable of heterodimerization with numerous partners." (PMID 36214621, 2022).
endometrial tumor (1 paper, 2022). "The fact that TGFB2 shares 2 β8 cysteines and an endometrial adenoma phenotype with INHA and INHBB implies that TGFB2 can heterodimerize with either to prevent endometrial tumor formation." (PMID 36214621, 2022).
Hyperinsulinemia (1 paper, 2009). An increased concentration of insulin in the blood. "Furthermore, our study shows that there is an altered relationship between ALK7 and INHBB expression in subjects with hyperinsulinemia, opening the possibility that activin B signaling is involved in metabolic control or that insulin affects the expression." (PMID 19275893, 2009).
Lewis lung carcinoma (1 paper, 2024). "Moreover, conditioned media from B16-F10, 4T1 or Lewis lung carcinoma (LLC) cultures similarly induced PIM3, INHBB and BCL3 expression, indicating that secreted factors of multiple cancer cell types induced rCap marker expression in cultured ECs." (PMID 39627185, 2024).
liver cancer (1 paper, 2021). An epithelial or non-epithelial malignant neoplasm that arises from the liver. "INHBA and INHBB showed opposing effects however in liver cancer where INHBA (HR = 0.62, p = 0.0086) was a strong positive predictor but INHBB (HR = 1.52, p = 0.025) was a potent negative predictor." (PMID 33819300, 2021).
lymph node metastasis (1 paper, 2020). "Univariate analysis demonstrated that high expression of INHBB (P < 0.001), age (P = 0.002), invasion depth (P < 0.001), lymph node metastasis (P < 0.001), distant metastasis (P < 0.001), and TNM stage (P < 0.001) corresponded with poor OS in CRC patients." (PMID 33083477, 2020). "High expression of INHBB was closely related to invasion depth (P < 0.001), lymph node metastasis (P < 0.001), distant metastasis (P < 0.001), and TNM stage (P < 0.001)." (PMID 33083477, 2020).
Miscarriage (1 paper, 2021). A pregnancy that ends at a stage in which the fetus is incapable of surviving on its own, defined as the spontaneous loss of a fetus before the 22th week of pregnancy. "Case 7665 has a duplication of INHBB, which encodes a subunit for the activin and inhibin proteins that play important roles in trophoblast growth and invasion, and altered mRNA or protein levels of these compounds are associated with miscarriage, severe PE, and FGR." (PMID 33413077, 2021).
Myocardial fibrosis (1 paper, 2025). "Additionally, members of the transforming growth factor-beta (TGF-β) superfamily (INHBA, INHBB, NOG) occupy central positions in the protein interaction network, reflecting the dual role of the TGF-β pathway (regulating myocardial fibrosis and vascular plaque stability) at different disease stages." (PMID 41283645, 2025).
ovarian tumor (1 paper, 2023). "Furthermore, previous studies have shown that INHBA, which is homologous to INHBB in tumor cells, can partially mediate the activation of CAF in breast and ovarian tumor models." (PMID 37858201, 2023).
plasma cell tumors (1 paper, 2022). "INHBB has a prodomain gain-of-function mutation that is also associated with plasma cell tumors." (PMID 36214621, 2022).
premature ovarian failure (1 paper, 2025). "Loss of INHBB function may impair activin-mediated signaling, leading to defective follicular maturation and contributing to premature ovarian failure." (PMID 41458559, 2025).
tumor (34 papers, 2009 to 2025). "Our study showed that activin B is a major player in activating fibroblasts into pro-tumorigenic CAFs, and for the first time proposed an underlying molecular mechanism for INHBB in GC in combination with tumor microenvironment." (PMID 37858201, 2023). "Since chemokines secreted by tumor cells recruit immune cells to the tumor sites, we explored the association between INHBB expression and expression of chemokines/chemokine receptors in GC." (PMID 36118865, 2022). "High INHBB expression is associated with a poor prognosis and is an independent risk factor for prognosis in GC, along with age and residual tumor." (PMID 36118865, 2022). "It is also important to note that in a recent study, miR-34a and miR-34b/c gene silencing decreased apoptosis and cell viability and increased tumor grade as well as inducing the expression of lymph node metastasis-associated genes, including INHBB, AXL, FGFR1, and PDFGRB." (PMID 38116556, 2023). "All these data suggested that INHBB may be a novel oncogene and associated with tumor progression, but the role of INHBB in GC remains unknown." (PMID 36118865, 2022). "C12orf56 was expressed at higher levels in normal samples, whereas EREG and INHBB were expressed at higher levels in tumor samples." (PMID 39883700, 2025). "In keeping with our above data, mice inoculated with INHBB-knockdown GC cells showed significant inhibition of tumor growth and decrease of tumor burden compared with those of tumors derived from control cells." (PMID 37858201, 2023). "Recently, INHBB has been the subject of many studies concerning liver, colorectal, and prostate cancers as a new tumor promoting biomarker." (PMID 37858201, 2023). "To further clarify the effects of INHBB in GC tumor microenvironment in vitro, we next verified the roles of INHBB on GC tumorigenicity in vivo." (PMID 37858201, 2023). "IL-1b (100 ng per mouse; in tumor; twice a week; for 2 weeks) significantly reversed the growth of subcutaneous INHBB-knockdown MGC-803 xenografts." (PMID 37858201, 2023). "In conclusion, our research revealed that INHBB creates a local tumor-promoting inflammatory environment between GC cells and fibroblasts, thus providing new evidence for the role of INHBB in the occurrence and development of GC." (PMID 37858201, 2023). "In order to investigate the potential roles of INHBB in cancer, INHBB pan-cancer expression levels in adjacent tumor and tumor tissues were analyzed based on The Cancer Genome Atlas (TCGA) database." (PMID 37858201, 2023). "According to our study, we provided evidence that INHBB can promote the proliferation, migration, and invasion of tumor cells." (PMID 37858201, 2023). "INHBA expression was significantly enriched in infiltrative tumor AOIs, while INHBB expression was significantly decreased compared to nodular tumor AOIs." (PMID 35986012, 2022). "The differential expression data of INHBB in tumor and normal tissues were extracted from several databases and genetic alterations of INHBB were assessed by cBioPortal." (PMID 36118865, 2022). "Analysis of RNA-Seq data for INHBB using FireBrowse showed a 1.33-fold increase in INHBB expression in tumour samples compared to normal." (PMID 36612143, 2022). "We further explored the INHBB expression in paired or unpaired adjacent normal and tumor samples by analyzing TCGA and GEO datasets and validated it in our cohort." (PMID 33083477, 2020). "INHBB is the subunit of inhibin, which regulates gonadal stromal cell proliferation negatively and has tumor-suppressor activity." (PMID 28424419, 2017). "Notably, INHBB overexpression significantly enhanced tumor metastasis by inducing epithelial-mesenchymal transition (EMT)." (PMID 41394399, 2025). "Elevated levels of crucial genes such as INHBB, CCDC80, and S100A11 could be significantly linked to tumor development, progression, and the modulation of the tumor microenvironment." (PMID 39850875, 2024).
tumor (continued). "This is because exome sequencing has revealed a tumor-suppressive role for INHBB." (PMID 37981656, 2024). "Interestingly, the expression of PIM3 and INHBB was increased in sorted HUVECs 16 h after coculturing with tumor cells, as compared to HUVEC monocultures, indicating that tumor cells were sufficient to induce upregulation of rCap markers." (PMID 39627185, 2024). "The results demonstrated upregulation of CX3CL1 and INHBB expressions in tumor tissues." (PMID 37886241, 2023). "GC cells p65/INHBB/activin B and fibroblasts p65/IL-1β signal loop led to the formation of a whole tumor-promoting inflammatory microenvironment, which might be a promising therapeutic target for GC." (PMID 37858201, 2023). "Altogether, these results indicated that INHBB may function as an oncogene in CRC, and patients with INHBB overexpression were more likely to progress to tumor metastasis, worse invasion depth, and TNM stage." (PMID 33083477, 2020). "In addition, ECM-receptor interaction was the major enriched pathway according to the results of KEGG analysis, suggesting INHBB expression may have a specific correlation with the tumor microenvironment in GC." (PMID 36118865, 2022). "Therefore, INHBB might be an oncogene and play roles in tumor proliferation, invasion, and migration." (PMID 33083477, 2020). "To evaluate the clinical significance of inhibin beta family genes (INHBA, INHBB, INHBC, and INHBE) in STAD, we investigated their interrelations and compared their expression levels between tumor and normal tissues." (PMID 39543755, 2024). "Furthermore, the present study found a strong correlation between the expression of target genes (IL10RB, INHBB, NEO1, PIK3R1, BCL2, ID4, and INHBA) and the infiltration of tumor-killing cells into the tumor immune microenvironment in HNC." (PMID 40647469, 2025). "These stocks are valuable for testing new mechanistic hypotheses for INHBB and INHBC reported as a tumor suppressor or an oncogene in prostate cancer, respectively." (PMID 37981656, 2024). "Based on the in vitro transcriptome analysis and validation of “cytokine-cytokine receptor interaction,” “PI3K-Akt signaling pathway” and “MAPK signaling pathway,” we measured the relative protein expression of TGFB2, INHBB, PIK3R3, ITGB8, NTRK, and CACNA1D in tumor tissue." (PMID 36386893, 2022). "Low expression of FABP4 in tumor tissues (p < 0.05) was validated in five datasets, the lower expression of PLXNB3, INHBB and NKAIN4 in tumor tissues was verified in three datasets (p < 0.05), and the decreased expression of HOXC9 and was validated in one dataset, respectively (p < 0.05)." (PMID 35721480, 2022). "Furthermore, 30 clinical CRC tissues (including tumor tissues and the corresponding adjacent tumor tissues as well as normal tissues) were collected, and the expression of FABP4, HOXC9, INHBB, NKAIN4, and PLXNB3 was determined using RT-PCR." (PMID 35721480, 2022). "The opposing effects of overexpression of INHBB and INHBC on the immortalized epithelial PNT1A cells and metastatic PCa PC3 cells indicates a switch in the function of these activins from inhibiting or regulating growth in normal epithelial cells to being pro-oncogenic in tumor cells." (PMID 36612143, 2022). "All together, these data show that the expression of INHBB, ANXA2, and TGFA ligands could be specifically up-modulated in PTCs vs. normal contralateral cells, thus supporting the hypothesis that their differential expression is finely regulated in normal tissues vs. tumor tissues." (PMID 20877637, 2010).
tumor (continued). "The results showed that, in the TCGA cohort, C12orf56 and RORC had higher expression in normal samples, while EREG, INHBB, MAGEA12, and MMP10 had higher expression in tumor samples; ASRGL1 showed no expression difference between normal and tumor samples." (PMID 39883700, 2025).